NPAP1 (nuclear pore associated protein 1)
Description:
May be involved in spermatogenesis.
Synonyms: C15orf2
Tractability: Antibody: its Gene Ontology location is reachable by antibodies, with high confidence.
Gene: Protein-coding gene on chromosome 15 (24,675,775 to 24,683,393, forward strand). Ensembl gene ENSG00000185823.
Subcellular location: Nucleus, nucleoplasm; Nucleus inner membrane
Subcellular location (Human Protein Atlas): Nucleoplasm; Plasma membrane; Vesicles
Gene Ontology:
Molecular function: structural constituent of nuclear pore
Biological process: protein import into nucleus; RNA export from nucleus; spermatogenesis
Cellular component: nucleoplasm; nuclear pore; nuclear inner membrane
Genetic constraint (gnomAD): Loss-of-function variants: 1 observed, 0.35 expected, observed/expected ratio (o/e) 2.85. That is too few expected variants to judge how well the gene tolerates losing a copy. Missense variants: 1,483 observed, 1,477.2 expected, observed/expected ratio (o/e) 1, 90% interval 0.96 to 1.05. Synonymous variants: 616 observed, 585.68 expected, observed/expected ratio (o/e) 1.05, 90% interval 0.98 to 1.12.
Homologues: Orthologues: chimpanzee NPAP1 (98% identical), macaque NPAP1 (88% identical), Drosophila melanogaster Nup153 (11% identical). Paralogues in human: POM121 (21% identical), POM121C (19% identical), NUP214 (17% identical), POM121L2 (17% identical), NUP153 (16% identical), POM121L12 (4% identical).
Diseases named in the same sentence as NPAP1 in open-access papers:
NPAP1 is named in the same sentence as 17 diseases in open-access papers, as found by Europe PMC text mining. Sharing a sentence is not in itself a finding about the gene and the disease. The quoted sentences say what the papers report.
Prader-Willi syndrome (5 papers, 2017 to 2022). "The finding is interesting since another nuclear pore associated protein (NPAP1) is believed contribute to Prader-Willi syndrome of which one of the major criteria is developmental delay/intellectual disability." (PMID 31694657, 2019). "MKRN3 is associated with Prader Willy Syndrome, NPAP1 both with Prader Willy Syndrome and Angelman Syndrome while DSCAML1 with Down Syndrome." (PMID 28993790, 2017). "NPAP1 gene encodes nuclear pore associated protein one which also located chromosome 15 and defects in this gene may be associated with Prader-Willi syndrome." (PMID 36059983, 2022). "Interestingly, rs3913226 (between NPAP1 and SNRPN) is located within chromosome 15q11–13, a region associated with Prader-Willi syndrome." (PMID 28642868, 2017).
lung carcinoma (2 papers, 2022 to 2023). "Of these, NPAP1 and NKRN3 are putative TSG, with prevalent loss-of-function alterations in melanoma and lung cancer, respectively." (PMID 37575996, 2023).
Obesity (2 papers, 2021 to 2024). Accumulation of substantial excess body fat. "Additionally, aside from SNURF-SNRPN and the SNORD gene family, the potential role of NPAP1 in obesity development should be considered." (PMID 38737552, 2024).
astrocytoma (1 paper, 2023). "Within the IDH mutant astrocytoma and oligodendroglioma groups, EPHA3 and NPAP1 surfaced as recurring genes potentially connected to the upregulation of INTS9." (PMID 37537630, 2023).
Hypertension (1 paper, 2017). The presence of chronic increased pressure in the systemic arterial system. "Three detected genes were recognized by previous studies, and the other 5 loci/genes (MAN1A1, LMO3, NPAP1/SNRPN, DNAL4, and RNA5SP455/KRT8P5) were novel findings, which had no strong main effect on hypertension and could not be easily identified by single-locus genome-wide studies." (PMID 28642868, 2017).
male infertility (1 paper, 2015). The inability of the male to effect fertilization of an ovum after a specified period of unprotected intercourse. "One exception is the NPAP1 gene (alias c15orf2) which has been linked to spermatogenesis and male infertility in human." (PMID 25950437, 2015).
non-small cell lung carcinoma (1 paper, 2022). A group of at least three distinct histological types of lung cancer, including non-small cell squamous cell carcinoma, adenocarcinoma, and large cell carcinoma. "A recent study has identified that NPAP1 is one of the potential genes which associated with the response to immune checkpoint inhibitors therapy in patients with non-small cell lung cancer." (PMID 36059983, 2022).
prostate enlargement (1 paper, 2025). "A UK Biobank‐based GWAS confirmed an increased OR for SNPs at PGR (OR 1.36), whilst additionally revealing two SNPs protective against prostate enlargement symptomatology, nearby other genes including MPPED1 and NPAP1 (OR 0.72 and 0.66, respectively)." (PMID 39187949, 2025).
NPAP1 also shares sentences with these, for which no sentence is quoted: Intellectual disability (2 papers); tumor (2); Angelman syndrome (1); cancer (1); developmental delay (1); Down syndrome (1); melanoma (1); oligodendroglioma (1); psychosis (1).